FGF1 (fibroblast growth factor 1)
Diseases named in the same sentence as FGF1 in open-access papers (continued):
Sharing a sentence is not in itself a finding about the gene and the disease.
diabetes (continued). "Taken together, above data further confirmed that FGF1 treatment ameliorated diabetes‐induced renal dysfunction." (PMID 30320493, 2018). "Taken together, FGF1 treatment reversed diabetes‐induced oxidative stress and nitrosative stress in kidney." (PMID 30320493, 2018). "Fibroblast growth factor 1 (FGF1), an effective control agent of blood glucose, plays an effective treatment role on diabetes‐induced renal injury." (PMID 30320493, 2018). "The FGF family has shown a great potential in the treatment of diabetes, particularly FGF-1, FGF-19 and FGF-2120." (PMID 27808173, 2016). "We also observed an increase in acidic FGF1 mRNA in diabetes (another known target of miR-133aa) and an established activator of ERK1/2 phosphorylation." (PMID 24428157, 2014). "The therapeutic potential of FGF1 in diabetes treatment also provides valuable insights for its potential clinical application in MASLD, especially given the significant progress made with FGF21—another member of the FGF1 family—in MASLD therapy and drug development." (PMID 41513602, 2026). "Additional studies are needed to determine how icv FGF1 affects these neurons in vivo and whether their transcriptional remodeling contributes to the maintenance of diabetes remission." (PMID 41371441, 2026). "Intact insulin signaling is required for diabetes remission induced by the central action of FGF1." (PMID 41072794, 2025). "In support of this hypothesis, we report that permanent AgRP neuron inactivation recapitulates the sustained diabetes remission induced by icv FGF1 in Lepob/ob mice." (PMID 40371641, 2025). "Additionally, FGF-1 inhibits diabetes-induced liver injury by decreasing oxidative stress and restoring autophagy." (PMID 38542166, 2024). "We found that FGF1 ameliorates diabetes‐induced hepatocyte apoptosis and elevated inflammation via suppressing RAGE expression, suggesting RAGE may be a potential therapeutic target for the treatment of DMLD." (PMID 33788387, 2021). "Moreover, exogenous FGF1 treatment can reverse diabetes‐induced suppression of brain‐derived neurotrophic factor (BDNF) level and elevated neuronal apoptosis, then ameliorate cognitive decline." (PMID 33788387, 2021). "Furthermore, FGF-1 treatment reduced diabetes-induced oxidative stress in mice with diabetic nephropathy." (PMID 34281287, 2021). "However, diabetes also increased anti‐inflammatory factor level (IL‐10), and FGF1 treatment further enhanced the level of IL‐10." (PMID 33788387, 2021). "Furthermore, FGF1 has been reported to block cellular stress and autophagy, and consequently ameliorates diabetes‐mediated hepatocyte apoptosis." (PMID 33788387, 2021). "The data suggest that FGF-1 treatment could ameliorate the levels of diabetes-induced inflammatory mediators in the retinas of diabetic rats." (PMID 34281287, 2021). "Fgf1 gene knockout mice further developed diabetes coupled with aberrant adipose enlargement." (PMID 35011683, 2021). "Recent literature has demonstrated that, in addition to inducing the remission of diabetes in rodent models, FGF1 induces robust activation of c-Fos and pERK1/2 in the ARH and median eminence (ME), however, the neuronal phenotypes and extent of neuronal activation in the ARH are less clear." (PMID 34987476, 2021). "Therefore, FGF-1 treatment can be considered as a novel therapeutic target for preventing the development of diabetes-induced retinal neurodegeneration." (PMID 34281287, 2021). "Exogenous fibroblast growth factor 1 (FGF1) has a great potential for the treatment of diabetes." (PMID 33788387, 2021). "In the present study, our results demonstrated that FGF-1 treatment could alleviate diabetes-related retinal complications in a diabetic rat model in vivo and ARPE-19 cells in vitro." (PMID 34281287, 2021).
diabetes (continued). "It is of great importance to note that subcutaneously injection of mouse FGF1 or intracerebroventricular injection of human FGF1 can significantly improve the insulin sensitivity and reduce the serum glucose levels in mouse models of diabetes." (PMID 35011683, 2021). "Mechanistic studies demonstrated that induction of cellular stress in diabetic liver was inhibited by FGF1 treatment, suggesting that reduction of cellular stress was a potential molecular mechanism in course of FGF1 treatment for diabetes-induced liver injury." (PMID 32194395, 2020). "Whether and how these cells might contribute to sustained FGF1-induced diabetes remission warrants additional study." (PMID 32895383, 2020). "In the present study, we determined whether FGF1 treatment reversed diabetes-induced oxidative stress by measuring glutathione levels and oxidative stress markers." (PMID 32194395, 2020). "Notably, the anti-diabetic effect is not secondary to weight loss, and the mechanisms and specific neuronal circuits by which FGF1 induce diabetes remission remains to be fully determined but likely involves the HPA axis." (PMID 32372975, 2020). "It confirmed our hypothesis that FGF1 treatment effectively improves diabetes-induced inferior spatial learning and memory function." (PMID 32460803, 2020). "The protective effect of FGF1 on diabetes-induced injury was demonstrated by significantly lower plasma ALT activity levels, TG levels, and hepatic lipid accumulation as well as suppressed cellular stress, reduced diabetes-induced hepatic apoptosis, and restored defective hepatic autophagy." (PMID 32194395, 2020). "Moreover, FGF1 blocked diabetes-induced morphological structure change, neuronal apoptosis and Aβ1–42 deposition and synaptic dysfunction in hippocampus." (PMID 32460803, 2020). "We found that diabetes remarkably suppressed FGF1 expression in hippocampus." (PMID 32460803, 2020). "Nevertheless, the effects and potential mechanisms of FGF1 against diabetes-induced liver injury are unknown." (PMID 32194395, 2020). "Furthermore, FGF1 administration significantly blocked diabetes-induced decrease of Bcl-2 expression and increase of Bax expression, subsequently upregulated Cleaved-Caspase3 expression (p < 0.05)." (PMID 32460803, 2020). "FGF1 treatment significantly suppressed diabetes‐induced ER stress." (PMID 30320493, 2018). "FGF1 treatment significantly attenuated the effect of diabetes on cellular stress." (PMID 30320493, 2018). "Since induction of cellular stress is the main and common mechanism of diabetes‐induced complication, we hypothesized that reduction of cellular stress is also the molecular mechanism of FGF1 treatment for DN." (PMID 30320493, 2018). "Moreover, it was found that FGF1 administration blocked diabetes‐induced oxidative stress though NOX2‐ROS‐Nrf2 signalling, and elevated ER stress evidencing with induction of ER stress makers in kidney." (PMID 30320493, 2018). "Here, we had confirmed that FGF1 significantly ameliorated diabetes‐induced nephropathy." (PMID 30320493, 2018). "To detect whether FGF1 treatment inhibited diabetes‐induced ER stress in kidney, we had detected the expression levels of ER stress makers." (PMID 30320493, 2018). "In addition to its ability to lower blood glucose levels without inducing hypoglycemia, FGF-1 exhibits promising potential in the treatment of complications associated with diabetes." (PMID 38542166, 2024). "The remarkably long-lived duration of this inhibitory effect is compatible with a role for reduced NPY/AgRP neuron activity in the effect of FGF1 to induce sustained diabetes remission in Lepob/ob mice, although additional studies are needed to test this hypothesis directly." (PMID 35917179, 2022). "Our results indicated that FGF-1 could effectively prevent retinal injury in diabetes." (PMID 34281287, 2021). "Furthermore, FGF-1 may be used to treat diabetes-related complications (i.e., those related to the heart, liver, kidney, and skin)." (PMID 34281287, 2021).
diabetes (continued). "Moreover, FGF1 treatment suppressed diabetes‐induced down‐regulation of Nrf2 expression." (PMID 30320493, 2018). "Remarkably, PNN digestion through ChABC administration completely prevents diabetes remission, indicating that the integrity of ARC PNNs is essential for the sustained glucoregulatory effect of FGF1." (PMID 40728680, 2025). "These considerations highlight important unanswered questions about interactions between FGF1, AgRP neurons, the HPA axis, and the pathogenesis of obesity and diabetes." (PMID 40371641, 2025). "Recently, FGF1 has been found to exert an unexpected metabolic role in regulating lipid metabolism and glucose homeostasis in obesity, MASLD, and diabetes." (PMID 40243151, 2025). "In this study, we found that diabetes obviously suppressed the expressions of BDNF and MAP 2 in the hippocampus when comparing with those in db/m mice, and which were abolished by FGF1 administration." (PMID 32460803, 2020). "In our study, diabetes markedly resulted in down-regulation of Nrf2, HO-1 and SOD2, an effect that was reversed by FGF1 treatment." (PMID 32194395, 2020). "In this study, diabetes significantly triggered PERK-eIF2α signaling and induced excessive apoptosis in the hippocampus, and FGF1 treatment blocked them." (PMID 32460803, 2020). "Studies in animal models of diabetes have demonstrated a significant advantage of FGF1 in glucose lowering: a lack of side effects, including those affecting the immune system." (PMID 41520078, 2026). "Despite these efforts, no FGF1 analogue capable of effectively lowering glucose levels and acting against diabetes has yet reached human clinical trials." (PMID 41520078, 2026). "Combined with evidence that FGF1 increases PNN assembly in the arcuate nucleus, our findings reveal a cell-type–specific model for how FGF1 elicits long-term reprogramming of hypothalamic circuits to achieve diabetes remission." (PMID 41371441, 2026). "A previous study showed that the protective effect of exogenous administration with FGF1 is dependent on RAGE; thus, inhibition of RAGE might be able to mimic the protective phenotype of FGF1 in diabetes." (PMID 37007029, 2023). "Because elevated hypothalamic Agrp and Npy mRNA levels are a characteristic finding in rodent models of diabetes, we wondered whether NPY/AgRP neuron inhibition might be a target for the antidiabetic action of FGF1 in the MBH." (PMID 35917179, 2022). "We therefore sought to determine whether FGF1 inhibits NPY/AgRP neurons and, if so, whether this inhibitory effect is sufficiently durable to offer a feasible explanation for sustained diabetes remission induced by central administration of FGF1." (PMID 35917179, 2022). "In this study, diabetes significantly reduced FGF1 expression in the CA1 of hippocampus, suggesting that FGF1 may be an key regulatory factor during DICD development." (PMID 32460803, 2020). "Considering that human FGF1 has potential therapeutic applications for accelerating wound repair and clinical treatment of chronic non-healing dermal ulcers in diabetes." (PMID 31578149, 2019). "Another study also reported that a low dose of FGF1 administered intracerebroventricularly resulted in sustained diabetes remission in mouse and rat models of T2DM, but it did not reduce corticosterone levels, suggesting that the role of the HPA axis in diabetes remission is questionable." (PMID 35052794, 2022). "Moreover, we found that diabetes triggers the elevated RAGE in hepatocytes, and FGF1 treatment blocks it, suggesting that RAGE may be a key target during FGF1 treatment of diabetes‐induced liver injury." (PMID 33788387, 2021). "Current mechanistic study had found that diabetes inhibits cAMP-response element binding protein (CREB) activity and subsequently suppresses brain derived neurotrophic factor (BDNF) level via coordinately regulating PERK signaling and PI3K/AKT signaling in hippocampus, which were reversed by FGF1." (PMID 32460803, 2020).
diabetes (continued). "Furthermore, it was observed that the diabetes- mediated suppression of PSD95, synaptophysin and synapsin-1 expressions in hippocampus were markedly reversed by GSK treatment, which is consistent with those in FGF1-treated group." (PMID 32460803, 2020). "Interestingly, icv leptin administration also normalizes excessive glucagon secretion and HPA axis activity in uncontrolled diabetes, whereas icv FGF1 injection does not — and yet, both appear to inhibit AgRP neurons, activate POMC neurons, and thereby increase net melanocortin signaling." (PMID 40371641, 2025). "Interestingly, although FGF1 has no hypoglycemic effect on type 1 diabetes mellitus, it can also improve the renal function of type 1 diabetes mellitus indicating the improvement function of FGF1 on diabetic nephropathy exists independently of the hypoglycemic effect." (PMID 33865387, 2021).
Obesity (28 papers, 2012 to 2026). Accumulation of substantial excess body fat. "Recent studies have demonstrated that suppression of IGFBP2 expression mitigates FGF1-induced activation of AMPK, supporting a critical role for IGFBP2 in mediating the therapeutic effects of FGF1 on obesity-associated hepatic steatosis." (PMID 40608848, 2025). "Our previous work in mice and human samples demonstrated that obesity and weight gain are associated with increased expression of the tumor-promoting growth factor FGF-1, which is produced by hypertrophic adipocytes." (PMID 35725493, 2022). "Further, this experiment assessed the role of mTORC2/Rictor in mediating the effect of FGF1 on obesity‐associated adipose tissue inflammation and insulin resistance." (PMID 32979037, 2020). "This study provides insight into the impact that genetic differences dictating the production of FGF1 has on the risk for developing obesity‐related metabolic disease in response to nutritional stress." (PMID 30972920, 2019). "Thus, FGF-1 ameliorated insulin resistance both in obesity induced insulin resistance mice, which is associated with its anti-inflammatory action and not through its glucose-lowering activity." (PMID 31866871, 2019). "Currently, three members of the FGFs family have been linked to obesity: FGF1, FGF15/19 and FGF21." (PMID 29652901, 2018). "Similar to ob/ob mice, DIO mice, which represent a more relevant model for obesity-driven metabolic disease, also displayed increased hepatic protein levels of Grp78 as well as ApoB after treatment with FGF1." (PMID 41541501, 2026). "Collectively, our data hint at the importance of m6A formation in the 3′ UTR of Fgf1 by METTL3 for the control of circulating FGF1 levels, suggesting regulation of factors implicated in diet-induced obesity." (PMID 40272887, 2025). "Together, our data highlight the connection between the METTL3/m6A pathway in cardiomyocytes, regulation of FGF1 levels, and modulation of systemic metabolism, overall affecting diet-induced obesity." (PMID 40272887, 2025). "Experimental interventions that increasing FGF-1 expression can prevent high-fat-diet-induced obesity and insulin resistance and reduce fasting blood glucose and triglyceride levels by regulating lipolysis in adipose tissues and hepatic glucose production." (PMID 40709999, 2025). "In subcutaneous adipose tissue biopsies taken from people with obesity before and after intentional weight gain, FGF1 expression increased significantly but only in those people who were classified as metabolically unhealthy." (PMID 37800138, 2023). "In a mouse model of obesity, FGF1 expression was elevated in mammary adipose tissue after estrogen withdrawal-induced weight gain." (PMID 37800138, 2023). "The purpose of this study was to understand the distinct effects of FGF1 exposure in ER-positive breast cancers that show sensitivity or resistance to estrogen deprivation in the context of obesity." (PMID 37608351, 2023). "In accordance with these findings, individuals with obesity have higher FGF1 secretion in SAT compared with lean individuals." (PMID 37252693, 2023). "Specifically, we found that FGF1 significantly reduced obesity‐induced infiltration and proliferation of macrophages by enhancing the adipocyte mTORC2/Rictor signalling pathway." (PMID 32979037, 2020). "In this present study, obesity triggered a robust systemic inflammatory profile were significantly inhibited by FGF-1." (PMID 31866871, 2019). "FGF1‐Tek mice were also more active than FVB controls – a behavioral trait that likely contributed to their resistance to obesity." (PMID 30972920, 2019). "In this study, we demonstrated that FGF-1 treatment significantly ameliorated obesity and TNF-α-induced stimulated cytokine secretion such as TNF-α and IL-6 as well as enhancing anti-inflammatory." (PMID 31866871, 2019).